MIR4453 (microRNA 4453)
Synonyms: hsa-mir-4453
Gene: MicroRNA gene on chromosome 4 (152,536,428 to 152,536,516, forward strand). Ensembl gene ENSG00000283792.
Homologues: Orthologues: chimpanzee MIR4453 (100% identical).